SCAMP4 (secretory carrier membrane protein 4)
Description:
Probably involved in membrane protein trafficking.
Synonyms: FLJ33847; SCAMP-4
Tractability: Antibody: UniProt predicts a signal peptide or a membrane-spanning region; the Human Protein Atlas places it where antibodies can reach. PROTAC: ubiquitination databases record sites on it.
Gene: Protein-coding gene on chromosome 19 (1,905,214 to 1,926,013, forward strand). Ensembl gene ENSG00000227500.
Subcellular location: Membrane
Subcellular location (Human Protein Atlas): Golgi apparatus; Vesicles; Lipid droplets; Plasma membrane
Gene Ontology:
Molecular function: protein binding
Biological process: exocytosis; protein transport
Cellular component: recycling endosome membrane; trans-Golgi network membrane; membrane
Genetic constraint (gnomAD): Loss-of-function variants: 20 observed, 31.14 expected, observed/expected ratio (o/e) 0.64, 90% interval 0.45 to 0.93. The upper end of that interval is the gene's LOEUF score, 0.93, which puts it in group 3 of 6, group 1 being the genes least tolerant of losing a copy. Missense variants: 302 observed, 289.37 expected, observed/expected ratio (o/e) 1.04, 90% interval 0.95 to 1.15. Synonymous variants: 152 observed, 125.77 expected, observed/expected ratio (o/e) 1.21, 90% interval 1.06 to 1.38.
Homologues: Orthologues: chimpanzee SCAMP4 (100% identical), dog SCAMP4 (92% identical), macaque SCAMP4 (92% identical), pig SCAMP4 (88% identical), guinea pig SCAMP4 (87% identical), rat Scamp4 (85% identical), mouse Scamp4 (83% identical), zebrafish scamp4 (60% identical), Drosophila melanogaster Scamp (43% identical), Caenorhabditis elegans scm-1 (41% identical). Paralogues in human: SCAMP5 (59% identical), SCAMP3 (45% identical), SCAMP1 (43% identical), SCAMP2 (41% identical).
Diseases named in the same sentence as SCAMP4 in open-access papers:
SCAMP4 is named in the same sentence as 3 diseases in open-access papers, as found by Europe PMC text mining. Sharing a sentence is not in itself a finding about the gene and the disease. The quoted sentences say what the papers report.
tumor (4 papers, 2021 to 2026). "In our report, we found that a higher SCAMP4 expression significantly correlated with poor overall survival, pointing to SCAMP4 as a possible tumor promoter." (PMID 34426610, 2021).
SCAMP4 also shares sentences with these, for which no sentence is quoted: cervical tumors (1 paper); gynecologic cancers (1).